SUOX (sulfite oxidase)
Description:
Catalyzes the oxidation of sulfite to sulfate, the terminal reaction in the oxidative degradation of sulfur-containing amino acids (By similarity). Can run in reverse direction and reduce nitrite to nitric oxide under physiologically relevant conditions, such as hypoxia.
Tractability: Small molecule: a structure with a bound ligand is known. PROTAC: ubiquitination databases record sites on it; its protein half-life has been measured.
Gene: Protein-coding gene on chromosome 12 (55,996,855 to 56,006,641, forward strand). Ensembl gene ENSG00000139531.
Subcellular location: Mitochondrion intermembrane space
Pathways (Reactome):
Metabolism: Sulfide oxidation to sulfate
Gene Ontology:
Molecular function: nitrite reductase activity; protein binding; heme binding; molybdopterin cofactor binding; sulfite oxidase activity; molybdenum ion binding; oxidoreductase activity
Biological process: sulfur compound metabolic process
Cellular component: mitochondrion; mitochondrial inner membrane; mitochondrial intermembrane space; mitochondrial matrix
Genetic constraint (gnomAD): Loss-of-function variants: 39 observed, 45.16 expected, observed/expected ratio (o/e) 0.86, 90% interval 0.67 to 1.13. The synonymous counts are far from expectation, so gnomAD's model fits this gene poorly and the ratio says little. Missense variants: 633 observed, 726.74 expected, observed/expected ratio (o/e) 0.87, 90% interval 0.81 to 0.93. Synonymous variants: 220 observed, 283.62 expected, observed/expected ratio (o/e) 0.78, 90% interval 0.69 to 0.87.
Gene-disease validity (ClinGen):
ClinGen rates the evidence that SUOX causes each of these diseases.
isolated sulfite oxidase deficiency (autosomal recessive): Definitive.
Homologues: Orthologues: chimpanzee SUOX (99% identical), macaque SUOX (98% identical), dog SUOX (89% identical), rabbit SUOX (89% identical), pig SUOX (88% identical), guinea pig SUOX (87% identical), mouse Suox (86% identical), rat Suox (85% identical), tropical clawed frog suox (59% identical), zebrafish suox (57% identical), Drosophila melanogaster shop (46% identical), Caenorhabditis elegans suox-1 (43% identical).
Diseases named in the same sentence as SUOX in open-access papers:
SUOX is named in the same sentence as 50 diseases in open-access papers, as found by Europe PMC text mining. Sharing a sentence is not in itself a finding about the gene and the disease. The quoted sentences say what the papers report.
isolated sulfite oxidase deficiency (15 papers, 2017 to 2025). "Isolated sulfite oxidase deficiency (ISOD) caused by sulfite oxidase gene (SUOX) mutations is a rare neurometabolic disease associated with ectopia lentis (EL)." (PMID 36303223, 2022). "PCT showed a SUOX variant in both parents, causative for sulfite oxidase deficiency, a lethal metabolic disorder matching the deceased child’s phenotype." (PMID 33742171, 2021). "Molybdenum cofactor deficiency and isolated sulfite oxidase deficiency are two rare genetic disorders that are caused by impairment of the mitochondrial enzyme sulfite oxidase." (PMID 33271457, 2021). "First, SO may be impaired by mutations in the SUOX gene, thus leading to isolated sulfite oxidase deficiency (ISOD)." (PMID 33488670, 2020). "Isolated sulfite oxidase deficiency (ISOD), which is caused by a mutation in the SUOX gene, is a life-threatening autosomal recessive inherited metabolic disorder." (PMID 39643979, 2024). "Primary or isolated sulfite oxidase deficiency (ISOD) is caused by biallelic pathogenic variants in the SUOX gene." (PMID 35192225, 2022). "Isolated sulfite oxidase deficiency (ISOD) is a rare autosomal recessive neuro-metabolic disorder caused by a mutation in the sulfite oxidase (SUOX) gene situated on chromosome 12." (PMID 34957373, 2021). "Isolated sulfite oxidase deficiency (ISOD) is an autosomal recessive disorder caused by a deficiency of sulfite oxidase, which is encoded by the sulfite oxidase gene (SUOX)." (PMID 31870341, 2019). "The SUOX gene is known to be involved in isolated sulfite oxidase deficiency (ISOD)." (PMID 38732138, 2024). "Isolated sulfite oxidase deficiency (ISOD), is a genetically determined disease caused by a mutation in the SUOX gene (locus 12q13.2)." (PMID 35053723, 2022). "Isolated sulfite oxidase deficiency (ISOD; OMIM #272300) is a devastating rare neurometabolic disorder due to biallelic pathogenic variants in the SUOX gene, that typically results in neonatal refractory epilepsy and progressive severe encephalopathy." (PMID 40440599, 2025). "Isolated sulfite oxidase deficiency (ISOD; OMIM #272300) is an ultra-rare autosomal recessive neurometabolic disorder caused by biallelic pathogenic variants in the SUOX gene located on chromosome 12q13.2." (PMID 40440599, 2025). "Isolated sulfite oxidase deficiency (ISOD, OMIM: 272300) is an autosomal recessive inherited neurometabolic disease caused by deficient activity of sulfite oxidase." (PMID 34025712, 2021). "In humans, SUOX is associated with isolated sulfite oxidase deficiency (ISOD), a disorder caused by lack of functional SUOX." (PMID 34001919, 2021).
Molybdenum cofactor deficiency (5 papers, 2012 to 2025). "It is also important to consider potential false positives arising from unknown or reported ultra-rare conditions such as molybdenum cofactor deficiency, isolated sulfite oxidase deficiency and DHTKD1 deficiency, in which α-AASA and oxo-PIP can also be found elevated." (PMID 40843901, 2025). "Molybdenum cofactor deficiency is associated with triple deficiency of XOR, AO and sulfite oxidase, due to defective synthesis of molybdopterin, which is a precursor of molybdenum cofactor for all three enzymes." (PMID 23203137, 2012). "Molybdenum cofactor deficiency, xanthinuria type III, a rare autosomal recessive neurodegenerative disorder is characterised by a combined deficiency of molybdenum cofactor-dependent enzymes sulfite oxidase, xanthine dehydrogenase and aldehyde oxidase." (PMID 28877755, 2017).
asthma (3 papers, 2021 to 2024). "Among 39 genes, SUOX gene were identified both in European and Japanese asthma-GWASs." (PMID 37875944, 2023).
microcephaly (3 papers, 2018 to 2024). A congenital or acquired developmental disorder in which the circumference of the head is smaller than normal for the person's age and sex. "Nevertheless, several previously published variants of SUOX were reported in patients with seizures, feeding difficulties, microcephaly, and brain atrophy.." (PMID 38572415, 2024). "This MOSC1 is similar to human “Sulfite oxidase, mitochondrial”, one of the microcephaly-related human proteins." (PMID 34583643, 2021). "Early onset refractory seizures, microcephaly, encephalopathy with or without dislocation of lens should cast a clue for the diagnosis of MOCD or isolated sulfite oxidase deficiency." (PMID 29696052, 2018).
vitiligo (3 papers, 2014 to 2024). Generalized well circumscribed patches of leukoderma that are generally distributed over symmetric body locations and is due to autoimmune destruction of melanocytes. "The same variant also showed strong cis associations with RPS26, and to a lesser degree, SUOX, and was associated with vitiligo." (PMID 24973796, 2014). "FGFR1OP and SUOX, have never been implicated towards vitiligo risk or pigmentation previously." (PMID 36008553, 2022). "Based on our prioritization pathway, we found that genetic variants of FGFR10P, SUOX, CDK5RAP1 and RERE have the potential to directly or indirectly contribute to the disease pathogenesis, suggesting that hitherto unexplored biological pathways may be involved in imparting vitiligo risk." (PMID 36008553, 2022). "Our analysis revealed genes like FGFR10P, SUOX, CDK5RAP1 and RERE that have never been implicated in vitiligo previously to have strong potentials to contribute to the disease pathogenesis." (PMID 36008553, 2022).
diabetes (2 papers, 2024 to 2025). "In summary, this SMR analysis explored the potential causal effects of OS-related genes on diabetes and its microvascular complications, highlighting the significant roles of TP53INP1, CHEK1, SUOX, and ICAM1 in the pathogenesis." (PMID 39199149, 2024).
ectopia lentis (2 papers, 2022 to 2024). "Sulfite oxidase deficiency (SUOX gene defect) is characterized by ectopia lentis and neurological involvement, such as ataxia, dystonia, neurological regression, and mental retardation." (PMID 39421111, 2024).
hepatocellular carcinoma (2 papers, 2024). A malignant tumor that arises from hepatocytes. "SUOX has shown great promise as a diagnostic and prognostic biomarker for various cancers, such as oral squamous cell carcinoma, and hepatocellular carcinoma." (PMID 38410384, 2024). "SUOX is a promising prognostic biomarker in a variety of cancers, such as hepatocellular carcinoma (HCC), intrahepatic cholangiocarcinoma (iCCA), etc.." (PMID 39199149, 2024).
mental disorder (2 papers, 2021 to 2023). A disease that has its basis in the disruption of mental process. "For the remaining 6 psychiatric diseases, a positive Wald ratio effect was observed for RHEBL expression and bipolar disorder, and negative Wald ratio effects for SUOX expression and anorexia risk, and for PTPN1 expression and major depressive disorder risk." (PMID 33417599, 2021).
Anorexia (1 paper, 2021). Lack of desire to eat (loss of appetite). "For instance, mutations in three genes our MR analyses linked to schizophrenia (RERE, KCNQ5) or anorexia (SUOX), respectively, are reported to cause monogenic diseases." (PMID 33417599, 2021). "Also, an increase in SUOX expression as it might be desirable to treat anorexia, colocalised with reduced hypothyroidism risk and additionally an elevated risk for rheumatoid arthritis and hypertension, warranting further safety investigations in follow up studies." (PMID 33417599, 2021).
deficiencies (1 paper, 2017). "Increased α-AASA urinary excretion is reported in other neurologic disorders including molybdenum cofactor and sulfite oxidase deficiencies." (PMID 28698725, 2017).
diabetic retinopathy (1 paper, 2024). "Our results show that SUOX is genetically associated with diabetic retinopathy, and increased SUOX expression due to cg22580629 is associated with a decreased risk of diabetic retinopathy." (PMID 39199149, 2024). "In addition, cg22580629 regulation of higher SUOX expression was associated with a lower risk of diabetic retinopathy." (PMID 39199149, 2024). "In addition, upregulation of SUOX expression by cg22580629 was linked to a reduced risk of diabetic retinopathy." (PMID 39199149, 2024). "Significantly, two other candidate genes, SUOX and CHEK1, which had not been intensively studied, were identified with a putative causal relationship with diabetic retinopathy." (PMID 39199149, 2024).
Epileptic encephalopathy (1 paper, 2018). A condition in which epileptiform abnormalities are believed to contribute to the progressive disturbance in cerebral function. "Molybdenum cofactor and isolated sulfite oxidase deficienciesfeat: epileptic encephalopathy, lens dislocation, hyperekplexia, multicystic encephalomalacia." (PMID 30559706, 2018).
gastric cancer (1 paper, 2024). A primary or metastatic malignant neoplasm involving the stomach. "A study performed by Yano and colleagues on 98 patients with advanced gastric cancer demonstrated that low expression of SUOX could be a prognostic biomarker in gastric cancer." (PMID 39643979, 2024).
leukemia (1 paper, 2007). A malignant (clonal) hematologic disorder, involving hematopoietic stem cells and characterized by the presence of primitive or atypical myeloid or lymphoid cells in the bone marrow and the blood. "Although genetic studies did not provide evidence that a common agent or genetic susceptibility factor caused the leukemias, the association between a SUOX gene locus and disease status in the presence of high tungsten and arsenic levels warrants further investigation." (PMID 17366837, 2007). "Although genetic studies did not provide evidence that a common agent or genetic susceptibility factor had caused the leukemias, the association between the SUOX –628 genotype and ALL, possibly interacting with high tungsten or arsenic levels, warrants further investigation." (PMID 17366837, 2007).
polycystic ovary syndrome (1 paper, 2024). A disorder that manifests as multiple cysts on the ovaries. "Genetically, SUOX may be a causal risk locus for Polycystic Ovary Syndrome (PCOS), suggesting the potential of SUOX in endocrine disorder diseases." (PMID 39199149, 2024).
Type I diabetes (1 paper, 2014). "Notably, this variant is in high LD with rs11171739 (r2 = 0.86 in CEU) previously implicated in blood cell cis association with RPS26 and SUOX and trans association with several targets, as well GWAS associations for Type I diabetes." (PMID 24973796, 2014).
cancer (4 papers, 2022 to 2024). A tumor composed of atypical neoplastic, often pleomorphic cells that invade other tissues. "Among them, ENSR00000052553 is the cancer-type-specific eRNA of HCC, which regulates the expression of SUOX and RDH16, and can be considered as a potential target eRNA for further treatment studies of HCC." (PMID 35646665, 2022).
genetic disorders (2 papers, 2021 to 2022). "Sulfite oxidase deficiency can also arise secondary to genetic disorders that disrupt de novo synthesis of molybdenum cofactor (MoCo), which is required for sulfite oxidase function." (PMID 35192225, 2022).
neurologic disorders (2 papers, 2017 to 2023). "Impairment in the activity of sulfite oxidase among these enzymes has been reported to cause neurological disorders and other diseases." (PMID 36671528, 2023).
heart diseases (1 paper, 2024). "Mutation or defect of SUOX can lead to a decrease or loss of sulfite oxidase activity, resulting in symptoms like nervous system damage, eye abnormalities, birth defects, and heart diseases." (PMID 39199149, 2024).
SUOX also shares sentences with these, for which no sentence is quoted: sulfite oxidase deficiency (8 papers); Encephalopathy (2); allergic disease (1); Ataxia (1); biotinidase deficiency (1); bipolar disorder (1); Brain atrophy (1); Cerebellar atrophy (1); Cerebral atrophy (1); cerebral edema (1); colorectal cancer (1); Dystonia (1); hyperekplexia (1); Hypertension (1); hypothyroidism (1); intrahepatic cholangiocarcinoma (1); major depressive disorder (1); Marfan syndrome (1); melanoma (1); metabolic disorder (1); nonketotic hyperglycinemia (1); Obesity (1); oral squamous cell carcinoma (1); ovarian carcinoma (1); rheumatoid arthritis (1); sarcopenia (1); schizophrenia (1); squamous cell carcinoma (1); tumor (1).